GBA1 (glucosylceramidase beta 1)
Description:
Glucosylceramidase that catalyzes, within the lysosomal compartment, the hydrolysis of glucosylceramides/GlcCers (such as beta-D-glucosyl-(1<->1')-N-acylsphing-4-enine) into free ceramides (such as N-acylsphing-4-enine) and glucose. Plays a central role in the degradation of complex lipids and the turnover of cellular membranes. Through the production of ceramides, participates in the PKC-activated salvage pathway of ceramide formation. Catalyzes the glucosylation of cholesterol, through a transglucosylation reaction where glucose is transferred from GlcCer to cholesterol. GlcCer containing mono-unsaturated fatty acids (such as beta-D-glucosyl-N-(9Z-octadecenoyl)-sphing-4-enine) are preferred as glucose donors for cholesterol glucosylation when compared with GlcCer containing same chain length of saturated fatty acids (such as beta-D-glucosyl-N-octadecanoyl-sphing-4-enine). Under specific conditions, may alternatively catalyze the reverse reaction, transferring glucose from cholesteryl 3-beta-D-glucoside to ceramide (Probable). Can also hydrolyze cholesteryl 3-beta-D-glucoside producing glucose and cholesterol. Catalyzes the hydrolysis of galactosylceramides/GalCers (such as beta-D-galactosyl-(1<->1')-N-acylsphing-4-enine), as well as the transfer of galactose between GalCers and cholesterol in vitro, but with lower activity than with GlcCers. Contrary to GlcCer and GalCer, xylosylceramide/XylCer (such as beta-D-xyosyl-(1<->1')-N-acylsphing-4-enine) is not a good substrate for hydrolysis, however it is a good xylose donor for transxylosylation activity to form cholesteryl 3-beta-D-xyloside. Can also metabolize plant glycosyl phytosterols such as glucosylstigmasterol.
Synonyms: GBA; GLUC; GCB
Tractability: Small molecule: a drug acting on it is in phase 2 or 3 trials; a structure with a bound ligand is known; a high-quality ligand is known; it has a high-quality binding pocket; it belongs to a druggable protein family. Antibody: UniProt places it where antibodies can reach, with high confidence; UniProt predicts a signal peptide or a membrane-spanning region. PROTAC: ubiquitination databases record sites on it; a small molecule that binds it is known.
Target class: Enzyme
Gene: Protein-coding gene on chromosome 1 (155,234,447 to 155,245,178, reverse strand). Ensembl gene ENSG00000177628.
Subcellular location: Lysosome membrane
Pathways (Reactome):
Metabolism: Glycosphingolipid catabolism
Metabolism of proteins: Association of TriC/CCT with target proteins during biosynthesis
Gene Ontology:
Molecular function: beta-glucosidase activity; glucosylceramidase activity; glucosyltransferase activity; protein binding; scavenger receptor binding; steryl-beta-glucosidase activity; signaling receptor binding; galactosylceramidase activity; hydrolase activity
Biological process: autophagy; cellular response to tumor necrosis factor; ceramide biosynthetic process; cholesterol metabolic process; glucosylceramide catabolic process; glycolipid biosynthetic process; lysosomal protein catabolic process; lysosome organization; mitochondrion organization; negative regulation of inflammatory response; negative regulation of interleukin-6 production; negative regulation of MAPK cascade; neuron projection development; positive regulation of neuronal action potential; regulation of TOR signaling; sphingosine biosynthetic process; termination of signal transduction; glycolipid catabolic process; regulation of lysosomal protein catabolic process; regulation of macroautophagy; beta-glucoside catabolic process; cellular response to starvation; establishment of skin barrier; protein catabolic process; regulation of membrane potential; and 8 more
Cellular component: extracellular exosome; lysosomal membrane; lysosome; endoplasmic reticulum; Golgi apparatus; lysosomal lumen; trans-Golgi network; extracellular region
Genetic constraint (gnomAD): Loss-of-function variants: 31 observed, 59.17 expected, observed/expected ratio (o/e) 0.52, 90% interval 0.39 to 0.71. The upper end of that interval is the gene's LOEUF score, 0.71, which puts it in group 2 of 6, group 1 being the genes least tolerant of losing a copy. Missense variants: 490 observed, 650.37 expected, observed/expected ratio (o/e) 0.75, 90% interval 0.7 to 0.81. Synonymous variants: 233 observed, 250.9 expected, observed/expected ratio (o/e) 0.93, 90% interval 0.83 to 1.03.
Gene-disease validity (ClinGen):
ClinGen rates the evidence that GBA1 causes each of these diseases.
Gaucher disease (autosomal recessive): Definitive. Gaucher disease (GD) is a lysosomal storage disorder encompassing three main forms (types 1, 2 and 3), a fetal form and a variant with cardiac involvement (Gaucher disease - ophthalmoplegia - cardiovascular calcification or Gaucher-like disease).
Parkinson disease (autosomal dominant): Definitive. A progressive degenerative disorder of the central nervous system characterized by loss of dopamine producing neurons in the substantia nigra and the presence of Lewy bodies in the substantia nigra and locus coeruleus.
Homologues: Orthologues: chimpanzee GBA1 (99% identical), macaque GBA1 (97% identical), dog GBA1 (90% identical), rabbit GBA1 (90% identical), pig GBA1 (90% identical), guinea pig GBA1 (88% identical), rat Gba1 (84% identical), mouse Gba1 (83% identical), tropical clawed frog GBA1 (54% identical), zebrafish gba1 (54% identical), Caenorhabditis elegans gba-3 (39% identical), Caenorhabditis elegans gba-4 (39% identical), and 4 more.
Diseases named in the same sentence as GBA1 in open-access papers:
GBA1 is named in the same sentence as 174 diseases in open-access papers, as found by Europe PMC text mining. Sharing a sentence is not in itself a finding about the gene and the disease. The quoted sentences say what the papers report.
Gaucher disease (527 papers, 2006 to 2026). "Gaucher disease (GD) is characterized by the accumulation of glucosylceramide within lysosomes due to mutations in the GBA1 gene, which encodes the enzyme glucocerebrosidase." (PMID 42072107, 2026). "Biallelic mutations in GBA1 are causative for Gaucher disease, whereas either monoallelic or biallelic mutations are a risk factor for Parkinson's disease." (PMID 41857000, 2026). "Gaucher disease (GD) is a lysosomal storage disorder caused by mutations in the glucocerebrosidase gene (GBA1), leading to acid β-glucosidase deficiency and the accumulation of glucosylceramide-derived glycosphingolipids." (PMID 41751844, 2026). "Gaucher disease (GD) is an autosomal recessive lysosomal storage disorder resulting from pathogenic variants in the GBA1 gene, which encodes the enzyme glucocerebrosidase." (PMID 41694855, 2026). "BACKGROUND: Gaucher disease (GD) is a lysosomal storage disorder caused by mutations in the GBA1 gene, leading to deficient glucocerebrosidase activity and accumulation of glucosylceramide in macrophages." (PMID 41559755, 2026). "Gaucher disease is a prototypical lysosomal sphingolipid storage disorder caused by pathogenic variants in GBA1, resulting in glucocerebrosidase deficiency and accumulation of bioactive lipids, including glucosylceramide and glucosylsphingosine (lyso-Gb1)." (PMID 42278317, 2026). "This occurs both in fibroblasts from healthy controls and from patients with Gaucher disease, in which GCase activity is already reduced due to a deleterious mutation in GBA1." (PMID 41540905, 2026). "GBA1 has been established as the causal gene for Gaucher’s disease (GD), the most common sphingolipidosis lysosomal storage disorder." (PMID 40333681, 2025). "Biallelic mutations in the glucosylceramidase beta 1 (GBA1) gene are the underlying genetic cause of Gaucher’s disease (GD), resulting in a deficient lysosomal hydrolase and subsequent accumulation of glycosphingolipids." (PMID 40333681, 2025). "While homozygous or compound heterozygous mutations in GBA1 cause Gaucher’s disease, heterozygous GBA1 variants have been identified as the most common genetic risk factor for PD, significantly increasing the risk of developing this disease." (PMID 40731814, 2025). "The GBA1 gene encodes the lysosomal enzyme β-glucocerebrosidase (GCase) and its deficiency underlies Gaucher disease." (PMID 41465340, 2025). "Gaucher disease (GD) is an autosomal recessive metabolic disorder caused by pathogenic variants in the GBA1 gene, which encodes the lysosomal hydrolase β-glucocerebrosidase (GCase)." (PMID 41300721, 2025). "Variants in the GBA1 gene, encoding the lysosomal enzyme glucosylceramidase beta 1 (GCase), are linked to Parkinson’s disease (PD) and Gaucher disease (GD)." (PMID 40362629, 2025). "The identification of new mutations in patients with symptoms referable to Gaucher disease increases the molecular knowledge related to the GBA1 gene and offers to clinicians significant support for the accurate diagnosis of the pathology." (PMID 40332757, 2025). "Gaucher disease (GD) is a rare inherited genetic disorder resulting from a recessive mutation in the GBA1 gene, which encodes the glucocerebrosidase (GCase) enzyme, resulting in the accumulation of glycolipids within the lysosomes of various body organs." (PMID 41163839, 2025). "Mutations in the human beta-glucocerebrosidase gene (GBA1) are associated with Gaucher disease, Parkinson’s disease, and Lewy body dementia." (PMID 40371365, 2025). "Gaucher disease (GD) is one of the most common autosomal recessive lysosomal storage diseases caused by variants in the acid β-glucosidase (GBA1) gene, which encodes the glucocerebrosidase enzyme." (PMID 41032223, 2025). "Gaucher disease (GD) arises from biallelic mutations in the GBA1 gene, resulting in defective acid β-glucosidase activity and the lysosomal accumulation of glucosylceramide (GlcCer) and glucosylsphingosine (GlcSph)." (PMID 40166071, 2025).
Gaucher disease (continued). "Gaucher disease (GD) is an autosomal recessive lysosomal storage disorder caused by biallelic mutations in GBA1, the gene that encodes the lysosomal enzyme β-glucocerebrosidase (GCase, EC 3.2.1.45)." (PMID 41465340, 2025). "Genetic variations in the GCase encoding gene GBA1 cause Gaucher’s disease (GD) and present the highest genetic risk factor to develop Parkinson’s disease (PD)." (PMID 40159502, 2025). "Mutations within the GCase-encoding gene GBA1 that impair enzyme function are the monogenic cause for Gaucher’s disease (GD)." (PMID 40159502, 2025). "This study aimed to identify GBA1 variants in Egyptian Gaucher disease (GD) patients residing in a region with high consanguinity and to correlate these genotypes with their clinical phenotypes." (PMID 41032223, 2025). "For example, Gaucher’s disease GBA1 mutations leading to defects in lysosomal sphingolipid metabolism cause α-synuclein accumulation." (PMID 40399377, 2025). "A challenge in diagnosing Gaucher disease is that the GBA1 gene is closely linked to a highly homologous pseudogene that harbors multiple disease-causing mutations." (PMID 40161497, 2025). "Biallelic GBA1 variants are associated with Gaucher’s disease, while monoallelic GBA1 variants are recognized as the most prevalent genetic risk factor for PD, with their prevalence varying among diverse ethnic groups 36–38,39–41." (PMID 39867380, 2025). "Gaucher’s disease is a rare autosomal recessive genetic disease caused by lysosomal Glucocerebrosidase (GBA1) enzyme deficiency." (PMID 39791178, 2025). "Gaucher disease (GD) is a genetic disorder caused by variants in the GBA1 gene, leading to a mutant glucocerebrosidase enzyme." (PMID 40566604, 2025). "Early diagnosis of patients suffering from Gaucher disease is of crucial importance in enabling timely therapeutic intervention, and mutation analysis of the GBA1 gene is a key step in this diagnostic process." (PMID 40332757, 2025). "Among them, Gaucher disease is the most common one and is distinguished by its three different subtypes, all caused by mutations in the GBA1 gene." (PMID 41511290, 2025). "We employed BFA1 to inhibit autophagosome–lysosome fusion and CBE to mimic the effect of GBA1 mutations, which causes Gaucher’s disease and predisposition to Parkinson's disease." (PMID 40456614, 2025). "Background/Objectives: Gaucher disease (GD) is an autosomal recessive lysosomal storage disorder caused by mutations in the GBA1 gene." (PMID 40430940, 2025). "Biallelic GBA1 pathogenic variants cause Gaucher disease (GD), an autosomal recessive lysosomal disorder with a variable phenotype, ranging from asymptomatic cases to severe systemic involvement." (PMID 40753162, 2025). "Gaucher disease (GD) is an autosomal recessive disorder caused by mutations in the GBA1 gene, which encodes the lysosomal enzyme glucocerebrosidase (GCase)." (PMID 40567527, 2025). "Gaucher disease (GD) is a lysosomal storage disorder caused by the failure of GBA1 (Glucosylceramidase Beta 1)." (PMID 41323100, 2025). "One well-studied example is Gaucher disease (GD), one of the most common LSDs, caused by mutations in the GBA1 gene encoding the lysosomal acid β-glucosidase, named glucocerebrosidase (GBA1)." (PMID 40141367, 2025). "Currently, some 721 mutations in the GBA1 gene associated with Gaucher disease have been identified, including missense, nonsense, small and large deletions/insertions, as well as rearrangements with the GBAP1 pseudogene." (PMID 40332757, 2025). "Sidransky syndrome is both autosomal recessive (when biallelic GBA1 variants, i.e., Gaucher disease (GD)) and autosomal dominant (when monoallelic GBA1 variants, i.e., GBA1 carrier) and spreads from prodromal to full-blown PD." (PMID 40508068, 2025). "Mutations in GBA1 is one of the most common genetic risk factors for Parkinson’s disease and Gaucher’s disease." (PMID 40371365, 2025).
Gaucher disease (continued). "Gaucher disease is characterized by a deficiency in the enzyme glucocerebrosidase (GCase) caused by mutations in the GBA1 gene." (PMID 40284413, 2025). "On HD8, rapid WGS resulted in two variants within the GBA1 gene that codes for glucosylceramide β-glucosidase 1, the defective enzyme in Gaucher disease." (PMID 40161497, 2025). "Gaucher disease (GD) is a prototype lysosomal storage disorder caused by biallelic mutations in the GBA1 gene." (PMID 41282474, 2025). "Background/Objectives: Pathogenic variants in the GBA1 gene, which encodes the lysosomal enzyme β-glucocerebrosidase, cause Gaucher disease (GD) and represent one of the strongest genetic risk factors for Parkinson’s disease (PD)." (PMID 41301891, 2025). "Gaucher disease is a rare autosomal recessive lysosomal storage disorder caused by mutations in the GBA1 gene that lead to defective lysosomal glucocerebrosidase or acid glucosidase." (PMID 40161497, 2025). "Among these, Gaucher disease (GD) is one of the most common and arises due to biallelic pathogenic variants in the GBA1 gene, which encodes the lysosomal enzyme glucocerebrosidase (GCase)." (PMID 40894035, 2025). "While homozygous mutations in the GBA1 gene cause Gaucher disease, heterozygous mutations in the GBA1 gene are a significant risk factor for PD and Lewy body dementia." (PMID 41185066, 2025). "The GBA1 gene encodes glucocerebrosidase, and damaging mutations in this gene are known to cause Gaucher's disease and increase the risk of Parkinson's disease." (PMID 40600167, 2025). "Gaucher disease (GD) is an autosomal recessive lysosomal storage disorder caused by biallelic mutations in the GBA1 gene, which encodes the enzyme β-glucocerebrosidase." (PMID 41301891, 2025). "The remaining heterozygous variant detected by the gene panel analysis in the proband lay at the GBA1 gene, underlying Gaucher disease, a different lysosomal disorder." (PMID 41463122, 2025). "Regarding GBA1 PD, most literature evidence on its association with cancer derives from studies in Gaucher disease (GD) patients carrying homozygous or compound heterozygous GBA1 mutations." (PMID 41300754, 2025). "Bi-allelic pathogenic GBA1 variants cause Gaucher disease (GD), whereas certain heterozygous missense variants increase the risk of Parkinson’s disease (PD), although the underlying mechanisms are unclear." (PMID 40753162, 2025). "The responsible gene is GBA1, although less frequently, Gaucher disease can be attributed to mutations in the prosaposin gene that codes for an activator (saposin C) of the lysosomal protein β-glucosidase acid." (PMID 40332757, 2025). "Gaucher disease (GD) is the most prevalent form and derives from deficiencies in the β-Glucocerebrosidase (GBA1) enzyme, leading to toxic accumulation of glucosylceramide." (PMID 41511290, 2025). "In fact, biallelic GBA1 mutation causes Gaucher’s disease, a mendelian LSD disorder affecting several organs and tissues due to cells accumulating fatty substances." (PMID 40399377, 2025). "Following the observation that the parents of individuals with Gaucher disease appeared to have PD more often than would be expected, heterozygous GBA1 variants were established as a significant risk factor for PD." (PMID 40834859, 2025). "Genotype–phenotype correlation remains incomplete in Gaucher disease, particularly for rare or compound heterozygous GBA1 variants." (PMID 41155380, 2025). "Special attention was given to lysosomal glucocerebrosidase (GBA1), the enzyme deficient in Gaucher disease in which lipid-laden macrophages are a hallmark." (PMID 40141367, 2025). "Biallelic mutations in the GBA1 gene, encoding GCase, result in the lysosomal storage disorder Gaucher disease, while heterozygous mutations have been identified as a common risk factor for PD." (PMID 40713630, 2025). "Gaucher disease (GD) is a lysosomal storage disorder caused by a deficiency in the GBA1‐encoded enzyme, β‐glucocerebrosidase." (PMID 38553911, 2024).